TERT (telomerase reverse transcriptase)
Diseases named in the same sentence as TERT in open-access papers (continued):
Sharing a sentence is not in itself a finding about the gene and the disease.
tumor (continued). "In other words, regardless of tumor grade or stage, TERT can be used as a predictor of the prognosis of the tumor." (PMID 37915019, 2023). "TERT activation meets the criteria of oncogenic addiction in HCC and could be actionable therapeutic target and a relevant tumor antigen." (PMID 37516867, 2023). "This is not surprising given the role of TERT in oncogenesis and its expression at every stage of tumor differentiation." (PMID 36909826, 2023). "Using TERT covalent inhibitor NU-1 to relieve the inhibition of non-homologous end-joining can induce immune infiltration and reduce tumor volume in CDX mice models." (PMID 38111043, 2023). "One tumor matched to methylation class “control tissue: inflammatory tumor microenvironment,” but morphologic and molecular features indicated a diagnosis of IDH-wildtype GBM; NGS revealed very low TERT VAF (0.09) in that case." (PMID 37919784, 2023). "Patient B (NF2-mutated tumours) on the other hand, had TERT promoter and NF1 mutations in all tumour grades, suggesting that a TERT promoter mutation is not an oncogenic driver, from Grade 2 to 3, as it was also present in the Grade 2 tumour." (PMID 36882706, 2023). "In addition, TERT 988 (988–997; DLQVNSLQTV) has been shown to stimulate CTL specifically against lysed tumour cells of various histological types expressing HER-2/neu or TERT." (PMID 38033865, 2023). "The presence of high entropy values in TERT‐mutant GBM may be attributed to the dysregulated cellular metabolism, which results in differences in tumor microenvironment between TERT‐mutant and wild‐type tumors." (PMID 38054695, 2023). "The transduction of the TERT gene or a catalytically inactive mutant protects various tumor cell lines from apoptosis, illustrating that the observed phenomena do not depend on the canonical functions of TERT." (PMID 37189709, 2023). "Since we recently published that only TCGA LUAD tumor samples express FL TERT and tumor adjacent normal tissues do not express FL TERT, we surmised that highly expressed splicing factors would be related to the re-emergence of FL TERT in the cancerous tissue." (PMID 37531400, 2023). "The detection rates of the studied mutations in urine were close to the expected rates based on the reported frequencies of these genetic alterations in tumor tissue (35.7% vs. 31.4–53.0% for the GPR126 sixth intron and 57.1% vs. 59.0–77.0% for the TERT promoter, respectively)." (PMID 36831030, 2023). "The median TERT copy number in tumor samples was 2.12 (IQR 1.96–2.56) and in non-tumor samples 1.96 (IQR 1.88–2.04)." (PMID 37858127, 2023). "The overexpression of TERT and HIF1A in clock KO cells points indeed to their clock-regulated expression and further emphasizes the importance of the clock in the cellular response to tumour promoting conditions." (PMID 37400829, 2023). "These tumours are characterised by the presence and absence of IDH1 and IDH2 mutations, and recently, TERT promoter alterations have been reported in around 20% of cases." (PMID 36042521, 2022). "Moreover, in primary TC tumours, there is a significantly inverse correlation between GABPA and TERT gene expression." (PMID 36394204, 2022). "For several tumor entities, also alternative telomere maintenance mechanisms have been described in which TERT is not involved (ALT, Alternative Lengenthing of Telomeres), but these mechanisms have not been observed in PCa." (PMID 35267575, 2022). "The genetic activation of TERT thus appears to more commonly allow HPV-negative cancer cells to achieve immortality in an HPV-independent context, but nevertheless also occurs in aggressive HPV-positive tumours." (PMID 36230545, 2022). "Besides, the clinicopathological features, including tumor grade, histology diagnosis, IDH status, 1p/19q codeletion, TERT promoter status, ATRX status, and MGMT promoter status, were also integrated." (PMID 36467068, 2022).
tumor (continued). "It is also important to identify approaches that will more rapidly induce telomere dysfunction so there is less dependency on relatively long periods of cell division in the absence of TERT for telomere reduction and tumor cell killing." (PMID 36130485, 2022). "Pathological and genetic examination confirmed that all tumor foci from the three mGBM patients were primary GBM featured with gain of chr.7 and loss of chr.10, lacking IDH1/2 mutations, high frequency of TERT promoter mutation." (PMID 34987659, 2022). "TERT-haploinsufficient tumor cells failed to produce xenografts in nude mice following transplantation, demonstrating that gene editing-mediated TERT deletion is a promising cancer treatment approach." (PMID 35328421, 2022). "Telomerase reverse transcriptase (TERT), which is required for elongation of telomeres, is highly expressed and activated in more than 90% of tumor cells, but not in normal healthy tissues." (PMID 35615262, 2022). "As a result, the EGFRvIII biomarkers may experience a larger accumulation during tumor growth and greater release after FUS-mediated BBB disruption compared with TERT C228T biomarkers." (PMID 34987650, 2022). "Based on the finding that TERT leads to different outcomes in IDH1- and IDH2-mutant tumours, we propose that genetic testing for IDH1, IDH2, and TERT promoter mutations in the context of other clinical factors, could be useful in patient stratification." (PMID 36042521, 2022). "Consequently, metastatic tumor mediators (ki-67, N-cadherin, AFP, and gene expression of cyclin D, TERT, VEGF, and MMP9) as well as functional parameters of metastatic seeds (CSCs) were dramatically downregulated in LC-DF(II) NPs." (PMID 36686682, 2022). "This is a key difference from other studies, which assessed TERT knockdown transiently, not allowing for the likely compensatory mechanisms that other factors exert in our cells and probably in actual tumor specimens re-expressing telomerase." (PMID 35053525, 2022). "Thus, the research and results link the markers regulating the tumor process and the telomerase complex TEP1 rs1760904, rs1713418, TERC rs12696304, rs35073794, TERT rs2736098, rs401681, which help explain the factors leading to the development of telocytes." (PMID 35892421, 2022). "PLMRS was significantly associated with age at diagnosis, tumor grade, IDH mutational status, 1p19q codeletion status, ATRX mutational status, MGMT promoter methylation status, TERT promoter status and histology, but not gender." (PMID 36203434, 2022). "In ICC samples, the expression value of HBV-integrated genes, including MET, WNT2, BRD9, and TERT, in tumor seems to be higher than the paired non-tumor tissues." (PMID 36123506, 2022). "Although TERT and ALT are hallmarks of tumor proliferation and attractive therapeutic targets, translational methods of imaging TERT and ALT are lacking." (PMID 33397920, 2021). "Furthermore, the results of studies have confirmed the interaction of telomerase/TERT with PI3K/AKT/mTOR and Wnt/β-catenin in various cancers which predominately participating in tumor invasion and metastasis and epithelial to mesenchymal transition (EMT)." (PMID 33869033, 2021). "It was found that TERT directly regulates miR500A by binding to the TCF binding elements (TBEs) located upstream of this gene, which results in inhibition of the Hedgehog signalling pathway and increased tumour invasiveness." (PMID 33713376, 2021). "The results show that, in LUAD, the expression level of TERT in tumor samples was significantly different from that in normal samples, and the expression level of TERT in tumor samples was not correlated with stage." (PMID 33905377, 2021).
tumor (continued). "This study investigated the patterns of HBV integration and correlated them with TERT (telomerase reverse transcriptase) alterations in paired tumor and non-tumor tissues." (PMID 34209079, 2021). "The tumour stroma (endothelial cells and fibroblasts) was consistently negative for TERT signals in all cases." (PMID 34011619, 2021). "In the present study, of 60 PTCs, 41 were BRAF-mutated (68.3%) and TERT promoter-mutated (3.5%), in contrast to no NRAS or KRAS mutation in the tumor tissues." (PMID 33915745, 2021). "TERT-telomere abnormalities might serve as useful biomarkers for HCC, but the prognostic values may differ with tumor characteristics and treatment." (PMID 33946181, 2021). "Surprisingly, miR500A was the only one able to increase the in vivo invasion capacity of tumour cells, while the miR532, which is not regulated by TERT, inhibited the invasiveness of parental tumour cells." (PMID 33713376, 2021). "The TERT promoter is hypermethylated in a number of telomerase-positive tumour samples while telomerase-negative normal tissues exhibited hypomethylation." (PMID 33802026, 2021). "Our results demonstrate that adjacent and non-adjacent tumor associated urothelium, non-invasive urothelium lesions as well as CIS surrounding the tumors are TERT mutated." (PMID 33562516, 2021). "The TERT promoter is an attractive target for tumor-specific therapy to selectively kill cancer cells without impacting somatic cell populations due to high levels of telomerase expression in cancer cells." (PMID 33802026, 2021). "Strikingly, TERT mRNA was visualised in the nuclear compartment only, thereby corroborating earlier studies suggesting a non-conventional role for TERT in tumour biology." (PMID 34011619, 2021). "In fact, somatic mutations that were not present in tumor DNA at the onset were instead identified in exo-DNA, in particular variants of ALK, ATRX, NF1, and TERT genes." (PMID 34072462, 2021). "In particular, the TERT‐mediated up‐regulation of miR500A results in the post‐transcriptional repression of PTCH1, triggering a ligand‐independent aberrant Hh signalling that significantly increases tumour cell invasiveness in a zebrafish xenograft model." (PMID 33713376, 2021). "Several studies have shown that TERT promoter mutations, mainly C228T, were detectable up to 10 years prior to UBC formation in urine liquid biopsy of patients without visible tumor." (PMID 34395278, 2021). "Results showed low or lack of h-TERT expression levels in the primary tumor and in normal tissue, respectively." (PMID 33863935, 2021). "Several cancer cell lines aligned closely with primary tumor TERT transcriptomes, while others did not." (PMID 33924498, 2021). "However, only the TERT inhibitor Costunolide was effective on the Stupp resistant 3D GBO model, reflecting the contribution of tumor microenvironment to therapy resistance." (PMID 33919246, 2021). "Unfortunately, we did not have enough tumour material to contemporaneously analyse TERT promoter status and TERT expression/activity, and further studies should be undertaken to extend and validate these findings." (PMID 34858860, 2021). "The higher levels of TERT mRNA expression in NMIBC and in high tumor grades suggest that reactivation of telomerase may differ between superficial and invasive, between low and high grade, and between low- and high-risk BC." (PMID 35223454, 2021). "Our results point to the crucial role of the TERT–miR500A–Hedgehog axis in tumour aggressiveness and highlight the therapeutic potential of targeting noncanonical TERT functions in cancer." (PMID 33713376, 2021). "TERT promoter mutation C250T and MGMT promoter methylation were significantly associated with tumor growth in univariable analysis but not in multivariable analysis." (PMID 32388499, 2020). "A putative relation between EGFR/KRAS mutation and the promoter methylation of CDH1, CDKN2Ap16, RASSF1A, TERT, and WT1 could influence tumor progression and therapy response." (PMID 32605217, 2020).
tumor (continued). "Furthermore, when considering the tumours with follicular pattern (FTC and encapsulated FV-PTC, n = 21), there was a significant difference, being the levels of TERT mRNA increased in the tumours that presented vascular invasion (p = 0.0446)." (PMID 32659948, 2020). "Tumours harbouring TERT gains (n = 80) showed a significantly higher prevalence for chromothripsis (61%, as compared to 44% in tumours without TERT gains, p < 0.01, chi square tests)." (PMID 32385320, 2020). "Similarly, clonogenicity of tumor cells treated with temozolomide was reduced particularly in PRPF19 and TERT knockdown cells." (PMID 32991787, 2020). "It functions by stimulating tumor-reactive CD8+ and CD4+ T-cell immunity specific for TERT." (PMID 33329574, 2020). "Taken together, these data support therapeutic application of TERT inhibitors to counteract tumor growth, regardless of telomere length of cancer cells." (PMID 32722398, 2020). "As expected, the frequency of TERT Th1 responders against the UCP peptide pool was greater in localized vs metastatic NSCLC (45% vs. 24%, respectively), pointing to a link between functional anti-TERT CD4 T cell immunity in peripheral blood and tumor progression." (PMID 32630460, 2020). "After adjustment for WHO grade, MGMT, Ki67, and TERT, molecular group of IDH1 and ATRX were associated with tumor growth in univariable analysis but not in the multivariable model." (PMID 32388499, 2020). "Malignant tumours from older patients present more frequently TERT expression (67% positive tumours vs. 33% negative tumours, p = 0.044)." (PMID 32659948, 2020). "Our previous results showed that PUF60 could regulate the expression of TERT and the mRNA expression of PUF60 and TERT showed a positive correlation, while their protein expression correlation in RCC cell lines and tumor tissues remained to be elucidated." (PMID 33061812, 2020). "TERT promoter mutation C250T and MGMT promoter methylation was significantly associated with tumor growth in univariable analysis but not in multivariable analysis." (PMID 32388499, 2020). "No such correlation was observed for CD8+ T cells, indicating that the magnitude of immune response, at least by CD8+ T cells, was not straightforwardly determined by the tumor size and availability of endogenous TERT as immunogen." (PMID 32570805, 2020). "For this, we assessed immune response to TERT by splenocytes of representative number of mice from each of the groups, slitting them into those rejecting tumors (n = 4), restricting tumor growth (n = 4), and not restricting tumor growth (n = 4)." (PMID 32570805, 2020). "By contrast, no benefit of the presence of a pre-existing anti-TERT immunity was observed in patients for whom the treatment failed to stabilize or reduce tumor burden." (PMID 32630460, 2020). "In vivo, TERT haploinsufficient tumor cells failed to form xenograft after transplantation to nude mice." (PMID 31963842, 2020). "As expected, the WTPE Hela cells grew into tumor mass (diameters ~2 cm) in all animals; whereas strikingly, the TERT+/− Hela cells failed to form any tumor xenotransplant in any of these animals." (PMID 31963842, 2020). "Without TERT, cells were more frequently immortalized using the alternative telomere elongation (ALT) mechanism, which caused increased tumor incidence." (PMID 33257697, 2020). "Despite the strong antitumor synergy, none of these immune checkpoint therapies showed improved TERT antigen-specific immune response in tumor-bearing mice." (PMID 31150505, 2019). "At the same time, no tumor was found in the TERT-hPDLSC groups, which means the cell of TERT-hPDLSCs did not have the potential tumorigenicity." (PMID 31065276, 2019). "Moreover, the clinical relevance of this finding is supported by investigation of the tumor material derived from a single patient treated with a combination of BRAF- and MEK-inhibitors resulting in undetectable levels of both ETS1 and TERT during therapy." (PMID 31391125, 2019).
tumor (continued). "Notably, the expression of 4 of these genes (TERT, ADPRM, SON and KRT32) were significantly higher in tumor tissues expressing chimeric transcripts compared to tissues without the fusion transcripts (bottom bar graphs)." (PMID 31429776, 2019). "Moreover, equivocal vascular invasion showed a significant association with TERT promoter mutations, suggesting that this histological feature could pinpoint the risk of a mutation-positive FT-UMP to a better extent than when only judging tumor cell in relation to the capsule." (PMID 31561592, 2019). "In line with the data from our cell models, a residual tumor of an anaplastic PXA case operated during combination treatment of dabrafenib and the MEK-inhibitor trametinib had lost expression of ETS1, cyclin D1 and TERT." (PMID 31391125, 2019). "Circulating TERT levels in plasma were estimated in 97 cases; 42 cases, including 18 of those who had high tumor TERT levels, were negative for TERT mRNA." (PMID 31772219, 2019). "Principle component analysis (PCA) was used to reduce the dimensionality of the TCGA-COAD and READ data sets for the tumor and normal samples, as well as for sigmoid and transverse normal colon samples, based on the expression of PTGS1, PTGS2, PTGES3, and TERT." (PMID 31614548, 2019). "Unlike most normal cells where there is lack of telomerase activity, upregulation of TERT transcriptional activity is detected in 80-90% of tumor cells." (PMID 31856825, 2019). "Although we detected NRAS Q12D mutant ctDNA at 1.4 copies per mL of plasma at one time point in patient 6, we did not detect TERT C228T mutant ctDNA at any time point in this patient, although it was detected in the tumor." (PMID 30719207, 2019). "Though TERT transcripts are highly elevated in BL compared to normal GCB cells (p < 0.001) the observed increase of telomere content between tumor cells and the normal GCB cells controls was not significant." (PMID 30926794, 2019). "Below, we present the prevalence of TERT and TERC amplifications in several tumour types." (PMID 29751586, 2018). "Increased TERT and TERC gene dosage has been detected frequently in a variety of human tumours, and clonal evolution of cells with increased TERT or TERC copy number has been observed, pointing towards a growth advantage in cells with increased TERT or TERC gene dosage." (PMID 29751586, 2018). "Further studies of primary tumor cells from patients with EBV-driven malignancies and suitable animal models will pave the way for a solidly based pre-clinical rationale for including TERT inhibitors in chemotherapy protocols for treating these malignancies." (PMID 29643934, 2018). "Whole-genome sequencing identified clonal expansion of HBV integration in the TERT locus in HCC tumors but not in adjacent non-tumor tissue DNA, suggesting its role in liver carcinogenesis." (PMID 30073017, 2018). "The mechanism of tumor progression robustly promoted by co-existing BRAF V600E and TERT promoter mutations is not known." (PMID 29422527, 2018). "The results show that stratification of high risk patient based on the DG score can be used as a prognostic factor for patients’ survival and it gives better results than previously known predictors such as tumor stage, MYCN amplification, age and TERT expression." (PMID 30012197, 2018). "Noteworthy, HCC and malignant pleural mesothelioma are tumours in which TERT gene is overexpressed but not 9ssociated with gene copy number gain." (PMID 29751586, 2018). "Our analysis showed that the presence of TERT promoter mutation and hypermethylation in TSG promoters were associated with HCV presence, but not with characteristics related to tumor progression." (PMID 30274313, 2018).